CD4 (CD4 molecule)
Diseases named in the same sentence as CD4 in open-access papers (continued):
Sharing a sentence is not in itself a finding about the gene and the disease.
infection (continued). "Some studies showed that the quantity of SARS-CoV-2–specific T-cells was not proportional to disease severity, or that the impaired virus-specific T-cells response is detected in CD4+ lymphocytes of severe patients in the acute phase of infection, but not in CD8+ lymphocytes." (PMID 37168853, 2023). "Our study identified the critical window of CD4+ T cell activation and differentiation during Plasmodium infection that is targeted by IL‐27, in which its transient neutralization enhances memory CD4+ T cells and improves protection against challenge infection without exacerbated immune responses." (PMID 37855243, 2023). "Subsets of mDCs, pDCs, CD4+, CD8+ T cells and Tregs were affected immune cell populations that indicate temporary and slight immunological changes that might increase the incidence of postoperative infection." (PMID 37885885, 2023). "T helper 17 cells (CD4-positive [CD4+] IL-17A+ and CD4+ IL-17F+), IL-17A- and IL-17F-producing CD8+ T cells, IL-17A-producing γδ T cells, and IL-17A-producing innate lymphoid cells (ILCs) were significantly increased in the skin samples 14 days after infection." (PMID 36695588, 2023). "Interestingly, we observed that activated (CD44+) CD4 T cells were significantly increased in frequency in aged mice compared to young mice on day 3 but not day 9 post-infection." (PMID 37852965, 2023). "Importantly, we found that F11‐dependent neutralization is not sufficient to protect animals from mortality, and a CD4 T cell‐dependent adaptive immune response is required for successful control of infection." (PMID 37767784, 2023). "Therefore, the presence of CD4 + and CD8 + T cells induced during natural infection and/or vaccination could indeed contribute to protection against future VOC." (PMID 36977691, 2023). "Interestingly, transdifferentiated BLaER1 cells displayed HIV-1 entry receptor CD4 expression and high surface level expression of both co-receptors CXCR4 and CCR5 indicating that they may be amenable to infection with CCR5- and CXCR4-tropic HIV-1." (PMID 37800914, 2023). "Overall, we hypothesize that a high CD4+ and CD8+ T cell response will reduce RNAemia upon challenge with a structurally heterologous virus, and correspondingly result in reduced magnitude of host response to challenge infection." (PMID 36969244, 2023). "An infiltration of CD4+CD25+T cells into the BF, and elevated expression of bursal TGFβ-1+ mRNA was observed at all time points following infection, irrespective of the strain or age of the birds, but CD4+TGFβ+cells and CD4+CD25+TGFβ+ cells only appeared in the BF at 28 dpi in younger birds." (PMID 37744374, 2023). "To investigate whether metabolic reprogramming of CD4+ T cells by P2RX7 is a key event for Th1 lineage differentiation, we performed a proteomic analysis on Foxp3-CD11a+CD4+ T cells from B6 and P2rx7-/- mice at day 6 of infection." (PMID 36993971, 2023). "Indeed, it was shown that SARS-CoV-2 infection after spike-based vaccination allows the development of T-cells specific against other SARS-CoV-2 antigens, and a rapid and extensive recall of spike-specific CD4 and CD8 occurs early after Delta or Omicron breakthrough infection." (PMID 37513709, 2023). "Studies have shown the correlation of Salmonella-specific CD4 and CD8 T cells with a positive outcome of vaccination with the licensed typhoidal vaccines Salmonella specific CD4 T cells can secrete IFN-γ in response to infection and are capable of homing to sites of infection." (PMID 37457702, 2023). "To confirm that IAV-specific CD4 and CD8 T cells were Ifnγ+, we stained cells from IAV-infected reporter mice with MHC I and MHC II tetramers containing immunodominant IAV nucleoprotein (NP) peptides, NP368-74, and NP311-325, respectively at days 10 and 40 post-infection." (PMID 37842651, 2023).
infection (continued). "Due to the high variability in treatments, we were also not able to assess the effects of individual substances on infection rates and whether there are synergistic or antagonistic effects on CD4+-T-cell numbers." (PMID 37152008, 2023). "CD4+ helper T cells (TH) and CD8+ cytotoxic lymphocytes (TC) have been implicated in protecting a group of healthcare workers lacking antibodies to SARS-CoV-2 against infection, despite their likely repeated exposure to the virus in hospitals." (PMID 38005881, 2023). "Endothelial injury due to trauma, infection, drugs, or autoantigens activate toll-like receptors (TLR) and trigger adventitial dendritic cells to release chemokines (CCL18-21) which further engage and recruit CD4 T-helper cells and macrophages into the arterial wall." (PMID 37033587, 2023). "Furthermore, others have shown that the partial depletion of CD4 T cells in BALB/c, close to the time of infection with a million L major parasites, modulates the long-term response from a Th2 to a Th1 mode, allowing the mice to contain the pathogen, again confirming the prediction." (PMID 37759652, 2023). "Upcoming studies associated with the mechanism of action will be conducted on PBMC, spleen cells and CD4 T cells harvested from S. mansoni-infected mice treated with PZQ at 18 mg/kg/day for 28 days to evaluate the Th1, Th2, and Th17 responses at different stages of the infection." (PMID 35446855, 2022). "However, ART does not eliminate HIV, and after depletion of CD4+ T cells during primary infection, some cells enter a resting state where HIV can remain persistently integrated into the host cell genome." (PMID 35745465, 2022). "Regarding the cell-mediated response related genes, NCCRP-1, TCR-γ, CD4, and CD8 were up-regulated in the sea bass brain with higher levels of NCCRP1 and TCR-γ upon infection with the mutant isolate at 3 dpi, which could be related to the up-regulation of IL-1b." (PMID 35215144, 2022). "However, because of the lack of consistent definition of virus-specific CD4+ T cell states across conditions and over time, the subtype-specific adaptations during infections are currently poorly characterized." (PMID 35829695, 2022). "Fourth, the infection time for most of the participants was unavailable, so the rate of CD4 count decline per year could not be assessed." (PMID 35260599, 2022). "Moreover, the proportion of infiltration of CD4+ and CD8+ T lymphocytes in saline, vaccine (Reo-2,177®), Clodronate liposome + Reo-V3 or cyclosporine + Reo-V3 groups were significantly lower (p < 0.0001) as compared to Reo-V3 group at day 9 post-infection." (PMID 35369435, 2022). "The IL-10 responses generated by both CD8+ and CD4+ T cells were present within 1 month of infection in response to a mix of pp71 and US3 proteins, but not in response to latency associated proteins, despite IFNγ-specific responses being detected from early timepoints post infection." (PMID 36558866, 2022). "Additionally, while all unvaccinated mice fully succumbed to infection in the absence of IL-17A, vaccinated mice neutralized of IL-17A in either the presence or absence of CD4+ or CD8+ T cells exhibited a ~35% survival rate 60 days post WT challenge." (PMID 36229573, 2022). "These follicular-like regulatory CD4+ T cell subsets have been postulated as critical regulators of adaptive responses in lymphoid organs, but so far have not been reported in the brain during infections." (PMID 36180478, 2022). "Notably, unlike HIV infection of CD4+ T-cells that results in cell lysis, the infection of microglia is non-lytic, thereby allowing for the persistence of HIV-1 in the brain." (PMID 35890062, 2022). "M-tropism, IFN-α, or LPS do not potentiate infection in CD4-negative astrocytes and neurons." (PMID 35975998, 2022). "In addition, CD4 knock-out mice (CD4 −/−) were capable of expelling tapeworms despite displaying no response to infection." (PMID 36558772, 2022).
infection (continued). "In addition, FoxP3+ CD25+ in CD4+ T cells increased with infection, both in frequency and number, in relation to non-infected mice." (PMID 36271272, 2022). "Individual CD4+ and CD8+ T‐cell responses directed against a total of 253 overlapping 15‐mer spike‐specific peptides were mapped in a cohort of COVID‐19 patients (n = 8), uninfected vaccinees (n = 16) and individuals who experienced both infection and vaccination (n = 11)." (PMID 35957961, 2022). "Underscoring the importance of T cells, earlier reports revealed that CD4+ and CD8+ T-cell responses against the Spike (S), Membrane (M), and Nucleocapsid (N) proteins of original SARS-CoV persisted for up to 11 years post infection and N-specific T-cell reactivity to 17 years post infection." (PMID 35812370, 2022). "Thus, CD4+ T cells during initial infection and CD4+ TRM cell formation are not essential for the remodeled AM phenotype in pneumococcus-experienced lungs." (PMID 35133985, 2022). "Interestingly, even in the unisex infection experiments in which there were no parasitic eggs and granuloma formation, PD-1 was still notably induced in liver CD4+ T cells." (PMID 35666747, 2022). "Antibodies, but not B and CD4+ T cells, decline up to 1 year following natural infection." (PMID 35139036, 2022). "Similarly, CD4+CD8+ memory Th cell counts, while always significantly lower in SPF compared to farm pigs, doubled in SPF pigs at the end of the experiment compared to levels prior to infection." (PMID 36006954, 2022). "To investigate whether a similar immune response characterized by diminished induction of Th2 cytokines could also be found at the infection site, we measured the percentages of CD4+IFN-γ+, CD4+IL-10+, and CD4+IL-4+ T cells in the challenged ears of control and vaccinated mice at 10 wpc." (PMID 35236861, 2022). "However, as expected, these individuals were infection-naïve without cross-reactivity (18% and 5%, respectively) whereas all the patients with pre-existing immunity had CD4+ and CD8 + T-cell response to the second dose of the vaccine (p = 0.042)." (PMID 35529539, 2022). "The presence of integrated provirus in resting CD4+ T cells at approximately one provirus per infected cell supports the observation that highly efficient cell-to-cell spread results in resting CD4+ T cell infection, but notably without leading to multiple proviral integrations." (PMID 35417711, 2022). "In fact, we found significantly elevated numbers of both CD4+ and CD4- iNKT cells in the spleen showing that there is an expansion of iNKT cells during acute NrHV infection which is however not detectable in the liver, the site of infection." (PMID 36159876, 2022). "Regardless of CLR treatment, CFA+GLA-SE/CDG immunization significantly elicited Mav CFA-specific CD4+CD44+CD62 L− T cells producing IFN-γ+IL-17A+, and IFN-γ+TNF-α+ but not IFN-γ+IL-2+ in the lungs in the CFA+GLA-SE/CDG-immunized group compared with those in the infection control group." (PMID 35499090, 2022). "Trans-infection occurs when DCs transfer viral particles without being infected by keeping them attached to its cell membrane or trapping them in non-lysosomal compartments until the viral synapse with CD4+ T cells occurs." (PMID 35802715, 2022). "Similarly, CD4 count decline appeared independent of the SPVL during the initial years post-infection." (PMID 35271687, 2022). "To determine whether ZFP36/ZFP36L1 were limiting factors for cytotoxic CD4+ T cells in vivo, we infected Zfp36fl/fl/Zfp36l1fl/flCd4cre mice with influenza A virus (PR8 H1N1) and measured CD4+ T cells in the lung 10 days following infection." (PMID 36385275, 2022). "Conversely, Tfh module scores were generally similar between acute and chronic LCMV CD4+ T cell clusters, although the Ly6c2-hi Th1 and Lag3-hi Th1 cell subsets from chronic LCMV infection did display a relatively increased Tfh signature compared to their acute infection counterparts." (PMID 36255051, 2022).
infection (continued). "In conclusion, CD4/CD8 ratio is a prognostic factor for acute SARS-CoV-2 infection independent of CD4 or CD8 alone, reflecting the negative impact on prognosis of those individuals whose immune response is disbalanced with an abnormal CD8+ T-cell depletion during the early response to the infection." (PMID 35814752, 2022). "Mutation was also characterized by a reduction in lung infiltration by CD4+ regulatory T (Treg) cells in the late infection/effector phase, 9 days post inoculation (p.i.), without significant differences in lung CD8 + T cells, or Treg cells at an earlier point (day 5) following infection." (PMID 35354833, 2022). "To assess whether CD101 is being downregulated on CD4 T cells after infection rather than these cells being directly depleted, we evaluated CD101 surface levels after in vitro HIV infection of sorted CD101- and CD101+ CD4 T cell cultures." (PMID 35867722, 2022). "The CD4+ T cells can differentiate into Th1 and Th2 cells to regulate the humoral immunity and cellular immune response, and the CD8+ T cells could differentiate into CD8+ cytotoxic T cells, which could directly eliminate intracellular pathogen infection." (PMID 36430809, 2022). "Eight days post-infection, CD4+ T cells were immunomagnetically enriched by negative selection." (PMID 35784297, 2022). "By showing that IL-10 overexpression during the chronic stages of the infection does not impact control of infection, our data demonstrate that the reduced migration of CD4+ T cells to the lung parenchyma is the critical mechanism whereby IL-10 antagonizes control of Mtb infection." (PMID 35935958, 2022). "In addition, the predominance of memory CD4+ and CD8+ T cells in CCC compared with NCC hearts highlights the critical role of the parasite-specific lymphocytic response in the course of the infection and the unique pathophysiological mechanisms related to this immune response observed in CCC." (PMID 36558736, 2022). "Notably, a rare case of laboratory-derived infection with Vpr-defective HIV-1 was characterized by markedly delayed seroconversion, suppressed viremia, and normal CD4+ T cell counts, consistent with reduced pathogenesis and failure to establish and maintain a significantly large tissue reservoir." (PMID 35417711, 2022). "The lack of efficacy of low concentrations of CD4-PP against P. aeruginosa after establishment of infection could be due to early formation of biofilm." (PMID 35821354, 2022). "Our research suggests that therapeutic targeting of S1P availability early in infection via SPHK inhibition and phosphorylated SAMHD1 modulation will aid in the development of strategies to prevent establishment of initial infection and hinder cell-to-cell transmission of HIV-1 in CD4 T cells." (PMID 35412343, 2022). "Using FLIPS, the infection frequency of the overall HIV proviruses (comprised of both the genetically-intact and the detective) per 106 CD4+ T cells and the infection frequency of genetically-intact HIV proviruses per 106 CD4+ T cells were calculated for all participants." (PMID 35916523, 2022). "Gut CD4+ T cells declined for all animals during the first 2–4 weeks of infection to levels that were lower than for historical ΔGY-infected PTMs, but then recovered with KV74 remaining at ~50% of pre-infection levels, and KV76 and KV52 showing a gradual return to baseline." (PMID 35714165, 2022). "Although the mechanism for HIV entry into these CD4-negative spermatozoon in vivo remains obscure, it may rely on cell-to-cell infection." (PMID 35253610, 2022). "This study, to our knowledge,is the first report on the proportion of gΔnef in patients with non-B infections and compared the responses with respect to CD4+ T cells and the proportion of gΔnef after KRG treatment between patients infected with subtype B and non-B over 10 years." (PMID 36312730, 2022).
infection (continued). "However, the down-modulation of CD4 after MDM infection did not change the relative proportions of low, intermediate and high CD4-expressing MDMs." (PMID 35622876, 2022). "While we observed that the percentage of peripheral CD4+ T cell per total T cells was decreased at 10 dpi similar to what we have published previously in other mouse strains, this effect was transient and no longer present at 6 months post infection (mpi)." (PMID 35033173, 2022). "In particular, almost no CD4+ T cells were present in the vaginal tissue 8 weeks post-infection." (PMID 36146734, 2022). "In summary, during chronic ASCs with HBeAg-negative infection, CD4+ T cells and their subsets, including Th1, Th2, Th17, Tfh, and Treg cells, showed high expressions of immune checkpoint molecules (TIM-3, PD-1, CTLA-4, and LAG-3) and decreased the secretion of cytokines." (PMID 35572697, 2022). "Thus, one third of infection-naïve HCWs without cross-reactivity had a lack of CD4+ T-cell response to the first dose of vaccine." (PMID 35529539, 2022). "To assess potential shifts in gene expression profiles that varied by infection and that spanned across all CD4+ T cell subsets, we performed module score analyses to compare Th1, Tfh, memory T cell, TCR signaling, and T cell dysfunction gene signatures across all of the CD4+ T cell clusters." (PMID 36255051, 2022). "Importantly, neither the infection status nor phenotypic and functional markers (e.g., CD4, Ki-67, CD169, and FoxO1) were considered in defining CNs; therefore, the microenvironment was defined using only the spatial phenotypic patterns." (PMID 35447093, 2022). "Patients with Gram-negative bacteremia who have HIV infection with CD4 < 200 cells/mm3, multidrug-resistant infections, and respiratory tract sources of infection may not be ideal candidates for this approach." (PMID 36137077, 2022). "However, frequencies of CD4+ICOS+Foxp3+ Treg cells during infection with non-lethal parasite remains significantly low (approximately 4%) by day 10th post infection." (PMID 35109868, 2022). "For example, viruses and intracellular bacteria trigger differentiation of CD4+ T cells into Th1 cells, which activate macrophages and cytotoxic T cells by secreting interferon (IFN)-γ, lymphotoxin (LT)-α, and interleukin (IL)-2 and consequently contribute to infection elimination." (PMID 36282845, 2022). "However, compared with infected WT controls, C. muridarum-infected Fcgr1−/− mice displayed increased innate immune cells (including monocytes, macrophages, neutrophils, and DCs) and reduced adaptive immune cells (CD3+ T cells and its CD4+ and CD8+ subsets), especially in the early infection." (PMID 36677333, 2022). "Secondary infection with B. canis resulted in significantly higher induction of CD4+ T lymphocytes in the lungs producing both IFN-γ and TNF-α while significant induction of trifunctional CD4+ T lymphocytes was noted during secondary infection with B. melitensis in the spleen." (PMID 36032120, 2022). "Infection is usually asymptomatic in immunocompetent individuals but may result in viremia and EOD in people with advanced immunosuppression, including people living with HIV with CD4 counts < 50 cells/μL." (PMID 36483572, 2022). "After 60 days of infection, both the total numbers of CD3+PD-1+, CD4+PD-1+, and CD8+PD-1+ T cells were decreased in the alphatoc/infected compared to the veh/infected mice, thus denoting that alphatoc may prevent T cell disfunction/anergy during the acute T. cruzi infection." (PMID 35154155, 2022). "The CD4+/CD8+ T-cell ratio increased significantly at week 4, and then there was no change from week 6 to 10, suggesting that CD4+ T cells might play an important role during the initial phase of PSC differentiation into hydatid cysts after infection." (PMID 36046744, 2022).